DUSP1 (dual specificity phosphatase 1)
Description:
Dual specificity phosphatase that dephosphorylates MAP kinase MAPK1/ERK2 on both 'Thr-183' and 'Tyr-185', regulating its activity during the meiotic cell cycle.
Synonyms: MKP-1; CL100; MKP1; PTPN10; HVH1
Tractability: Small molecule: a structure with a bound ligand is known; a high-quality ligand is known. PROTAC: UniProt records ubiquitination sites on it; ubiquitination databases record sites on it; a small molecule that binds it is known.
Target class: Phosphatase; Serine/threonine/tyrosine protein phosphatase; Enzyme; Protein Phosphatase
Gene: Protein-coding gene on chromosome 5 (172,766,992 to 172,771,198, reverse strand). Ensembl gene ENSG00000120129.
Subcellular location: Nucleus
Subcellular location (Human Protein Atlas): Nucleoli; Cytosol
Pathways (Reactome):
Signal Transduction: Negative regulation of MAPK pathway; RAF-independent MAPK1/3 activation
Gene Ontology:
Molecular function: protein binding; protein tyrosine phosphatase activity; protein tyrosine/serine/threonine phosphatase activity; MAP kinase tyrosine/serine/threonine phosphatase activity; mitogen-activated protein kinase binding; protein serine/threonine phosphatase activity; growth factor binding
Biological process: cellular response to chemokine; negative regulation of cell adhesion; negative regulation of monocyte chemotaxis; negative regulation of p38MAPK cascade; endoderm formation; negative regulation of MAPK cascade; negative regulation of meiotic cell cycle; peptidyl-serine dephosphorylation; peptidyl-threonine dephosphorylation; regulation of mitotic cell cycle spindle assembly checkpoint; cellular response to hormone stimulus; intracellular signal transduction; negative regulation of apoptotic process; negative regulation of cell population proliferation; negative regulation of DNA biosynthetic process; negative regulation of ERK1 and ERK2 cascade; positive regulation of apoptotic process; response to calcium ion; response to cAMP; response to estradiol; response to glucocorticoid; response to hydrogen peroxide; response to light stimulus; response to retinoic acid; response to testosterone
Cellular component: cytoplasm; nucleus
Genetic constraint (gnomAD): Loss-of-function variants: 10 observed, 24.53 expected, observed/expected ratio (o/e) 0.41, 90% interval 0.25 to 0.69. The synonymous counts are far from expectation, so gnomAD's model fits this gene poorly and the ratio says little. Missense variants: 425 observed, 435.14 expected, observed/expected ratio (o/e) 0.98, 90% interval 0.9 to 1.06. Synonymous variants: 262 observed, 194.17 expected, observed/expected ratio (o/e) 1.35, 90% interval 1.22 to 1.5.
Homologues: Orthologues: chimpanzee DUSP1 (100% identical), macaque DUSP1 (99% identical), dog DUSP1 (98% identical), rat Dusp1 (97% identical), mouse Dusp1 (96% identical), rabbit DUSP1 (96% identical), guinea pig DUSP1 (94% identical), pig DUSP1 (92% identical), tropical clawed frog dusp1 (78% identical), zebrafish dusp1 (71% identical). Paralogues in human: DUSP4 (64% identical), DUSP5 (47% identical), DUSP2 (45% identical), DUSP16 (31% identical), DUSP7 (31% identical), DUSP8 (31% identical), DUSP6 (31% identical), DUSP9 (29% identical), DUSP10 (27% identical), SSH1 (25% identical), SSH2 (25% identical), SSH3 (22% identical), and 19 more.
Diseases named in the same sentence as DUSP1 in open-access papers:
DUSP1 is named in the same sentence as 291 diseases in open-access papers, as found by Europe PMC text mining. Sharing a sentence is not in itself a finding about the gene and the disease. The quoted sentences say what the papers report.
breast carcinoma (55 papers, 2006 to 2026). "For example, during neoadjuvant chemotherapy (doxorubicin/cyclophosphamide) in breast cancer patients, increased DUSP1 levels were associated with increased residual tumor burden post-chemotherapy." (PMID 41158869, 2025). "An early report on breast cancer (BC) showed that DUSP1 expression is associated with poorly differentiated or late-stage tumours." (PMID 40943262, 2025). "DUSP1 encodes a phosphatase signaling protein of the MAPK pathway that is over-expressed in malignant breast cancer cells and inhibits apoptotic signaling." (PMID 32024846, 2020). "Meanwhile, irregular menstruation was significantly linked with increased DUSP1 methylation only in patients with ER-positive (OR 3.564, 95% CI 1.691–7.511) and PR-positive (OR 3.902, 95% CI 1.656–9.194) breast cancer." (PMID 28220843, 2017). "A case-control study (423 breast cancer cases, 509 controls) and a case-only study (326 cases) were conducted to evaluate the association of DUSP1 promoter methylation with breast cancer risk and clinicopathological characteristics." (PMID 28220843, 2017). "Higher expression of DUSP1 was also associated with reduced sensitivity of many other oncologic drugs, such as bortezomib, paclitaxel, mechlorethamine, tamoxifen, and doxorubicin in breast cancer." (PMID 41158869, 2025). "Thus, CTCF displacement particularly impacts in 3D genes, by changing their contact environment through TADs fusion as shown for the 3D down gene DUSP1 whose expression is associated with an increased risk of metastasis and shorter overall survival in breast cancer." (PMID 38565950, 2024). "Emerging evidence highlights that DUSP1's role is context-dependent on human cancers, including breast cancer (BC)." (PMID 41744846, 2026). "Studies have shown that DUSP1 is an important survival protein in breast cancer cells and a key downstream component of ERBB2 signaling." (PMID 40852352, 2025). "The study indicates that increased DUSP1 levels can cause anti-HER2 therapy resistance, and disruption of HER2+ DUSP1 signaling has more benefit to treat breast cancer, suggesting that DUSP1 is involved in immunotherapy resistance directly or indirectly." (PMID 41158869, 2025). "In breast cancer patients, the highest frequency of DUSP1 promoter methylation was observed in both tumor DNA and peripheral blood leukocytes (PBLs) DNA." (PMID 41158869, 2025). "In breast cancer, the use of Trastuzumab (a monoclonal antibody) to treat HER2-positive breast cancer decreased DUSP1 expression, activated JNK, and increased cell apoptosis." (PMID 41158869, 2025). "Partially, krüpple-like transcription factor 5 (KLF5) regulates ERK-induced DUSP1-Ser359/364 phosphorylation that promotes breast cancer cell survival, and this phosphorylation is essential for DUSP1 protein stabilization." (PMID 41158869, 2025). "Further research is needed to fully understand the complex interplay of DUSP1 with other signaling pathways and its potential as a therapeutic target in breast cancer." (PMID 41158869, 2025). "As an antiapoptotic phosphatase, DUSP1 can act as an oncogene in gastric cancer, breast cancer, and osteosarcoma." (PMID 36545243, 2022). "Glucocorticoids exerts anti-proliferative and anti-apoptotic activity on breast cancer epithelial cells, at least in part, via modulating transcriptional regulation of genes encoding cell survival pathways such as SGK1 and MKP1/DUSP1." (PMID 33604794, 2021). "DUSP1 is involved in the epithelial-to-mesenchymal transition, regulation of breast cancer stem cells (CSCs) and signal transduction." (PMID 32646377, 2020). "Among the genes negatively regulating apoptosis, DUSP1 provided the strongest prognostic signal in HER2-enriched breast cancers." (PMID 32024846, 2020). "DUSP1 mediates breast cancer proliferation and chemotherapy resistance by inhibiting JNK pre-apoptotic signaling pathway." (PMID 31338333, 2019).
breast carcinoma (continued). "DUSP1 can promote carcinogenesis of prostatic cancer, pancreatic cancer, lung cancer, breast cancer and gastric cancer." (PMID 29558404, 2018). "Soybean intake (>1 times/week) was significantly correlated with increased DUSP1 methylation only in patients with ER-negative (OR 2.978, 95% CI 1.245–7.124) and PR-negative (OR 2.735, 95% CI 1.315–5.692) breast cancer." (PMID 28220843, 2017). "Further validation of the association of environmental factors, including fruit and soybean intake, and irregular menstruation, with DUSP1 methylation by hormone receptor status in breast cancer should be undertaken." (PMID 28220843, 2017). "DUSP1 methylation was detected in 5.2% (22/423) breast cancer cases and 4.9% (25/509) controls in PBL DNA." (PMID 28220843, 2017). "The promoter regions of the DUSP1 and MKP1 genes have been found hypermethylated in oral squamous cell carcinoma and breast cancer, respectively." (PMID 28931650, 2017). "Our study is the first to explore the putative effects of soybean consumption on DUSP1 promotor methylation in breast cancer." (PMID 28220843, 2017). "The biological significance of DUSP1 hypermethylation in breast cancer should be addressed in future in vitro studies." (PMID 28220843, 2017). "PR had a positive correlation with DUSP1 expression in 30 human breast cancer cell lines by binding to two progesterone response elements downstream of the DUSP1 transcriptional start site to upregulate DUSP1 promoter activity." (PMID 28220843, 2017). "Several DUSP family members are thought to be involved in breast cancer metastasis including DUSP1, DUSP4, and DUSP6." (PMID 26859151, 2016). "DUSP1 is overexpressed in breast carcinomas compared to normal mammary tissue, with greater expression in infiltrating carcinomas than in situ carcinomas." (PMID 26859151, 2016). "In our study, several genes of the top 10 down-regulated DEGs such as DUSP1, FOXA1, MLPH was implicated in the development of breast cancer." (PMID 26103053, 2015). "DUSP1 inhibits apoptosis in human mammary epithelial and breast carcinoma cells and its expression is upregulated in many breast cancers." (PMID 22646717, 2012). "PTTG2 has been implicated in glioblastoma tumorigenesis as well as in head and neck squamous cell carcinoma, UTS2 has been reported to possess prognostic value in colorectal and breast cancers, TRAT1 in early breast cancer prognosis and DUSP1 in sarcoma progression." (PMID 39478658, 2025). "The relationship between DUSP1 and AP-1 network was reported in breast cancer." (PMID 37057290, 2023). "Therefore, we suggest that shikonin induces the expression of DUSP1 and DUSP2 which consequently switches off JNK and p38 MAPK pathways and causes cell cycle arrest and apoptosis in breast cancer cells." (PMID 29422643, 2018). "Therefore, our results suggest that shikonin induces the expression of DUSP1 and DUSP2 which consequently switches off JNK and p38 MAPK pathways and causes cell cycle arrest and apoptosis in breast cancer cells." (PMID 29422643, 2018). "Therefore, we cannot conclude any association between DUSP1 methylation in PBL DNA and breast cancer risk (OR 0.79, 95% CI 0.414–1.504, P = 0.472)." (PMID 28220843, 2017). "Given the very low (3.23–5.2%) methylation frequency in PBL DNA, DUSP1 methylation has potential as a biomarker in non-invasive breast cancer diagnosis if we can detect DUSP1 methylation from circulating cell-free DNA in plasma that is released by breast tumour cells." (PMID 28220843, 2017). "Given the lack of research on DUSP1 methylation in breast cancer in epidemiological studies, we first investigated the association between DUSP1 methylation in PBL DNA, interactions with environmental factors, and breast cancer risk." (PMID 28220843, 2017).
breast carcinoma (continued). "In addition to their potential role in immune regulation, studies have discussed the association of DUSPs namely DUSP1, DUSP4 and DUSP6 in oncogenesis especially in the epithelial-to-mesenchymal transition of breast cancer cells and the maintenance of cancer stem cells." (PMID 31035605, 2019). "Therefore, we concluded that there was not enough evidence for DUSP1 methylation in PBL DNA as a biomarker for breast cancer risk assessment." (PMID 28220843, 2017). "DUSPs such as DUSP1, DUSP4, and DUSP6 are involved in EMT and breast cancer stem cell (CSC) activity regulation." (PMID 41158869, 2025). "DUSP1 is a upregulated DDM DEG for both DFP treatment of MDA-MB-231 cells and JIB-04 treatment of MCF-7 cells, whereas its average expression in breast cancers is more than 2-fold reduced as compared to normal breast tissues." (PMID 41279823, 2025). "It was reported that in breast cancer AP-1 transcription factor components, i.e., JUN, JUNB, FOS, FOSB, in addition to DUSP1, EGR1, NR4A1, IER2 and BTG2, behave as a conserved co-regulated network 14, most of which are transcriptional factors." (PMID 37057290, 2023). "Both measures with high ranks indicated 5 SNPs (SALL1 rs10521222; HLA-DQA1 rs9271608; DUSP1 rs17658229; APOC1 rs4420638; and TRAIP rs2352975) and 3 lifestyles (duration of OC and E + P use and BMI) as the most influential variables for breast cancer." (PMID 33441805, 2021). "Inhibition of DUSP1 and DUSP6 induces apoptosis of highly aggressive breast cancer cells through the increased activation of MAPK signaling." (PMID 31035605, 2019). "The results of RNA-seq showed that shikonin induces the expression of DUSP1 and DUSP2 in breast cancer cells." (PMID 29422643, 2018). "We successfully detected DUSP1 methylation in both PBL DNA and tumour DNA from 155 breast cancer patients." (PMID 28220843, 2017). "Here we show that DUSP1, DUSP4, and DUSP6 are involved in epithelial-to-mesenchymal transition (EMT) and breast cancer stem cell (CSC) regulation." (PMID 26859151, 2016). "Taken together, these data indicate a novel chromatin-anchored role for DUSP1 and DUSP4 in mesenchymal breast cancer cells." (PMID 26859151, 2016). "DUSP1, DUSP4, and DUSP6 were constitutively expressed in both epithelial MCF-7 and mesenchymal MDA-MB-231 breast cancer cell lines." (PMID 26859151, 2016). "The increased DUSP1 expression in breast cancer is inversely correlated with JNK activity and markers of apoptosis, suggesting an anti-apoptotic role of DUSP1 via its activity towards JNK." (PMID 24409315, 2014). "In vitro models show that combined inhibition of MKP1 and HER2 actually leads to enhanced cell death in breast cancer cells, which is consistent with other studies showing that combined approaches targeting both HER2 and DUSP1 were more efficacious than those targeting HER2 alone." (PMID 41301877, 2025). "Overexpression of DUSP1 was found to inhibit the JNK protein (which belongs to the MAPK pathway), and impede mechlorethamine, doxorubicin, paclitaxel, and doxorubicin + mechlorethamine-mediated apoptosis in breast cancer in vivo." (PMID 41158869, 2025). "Knockdown of DUSP1, DUSP4, and DUSP6 involved in the formation of CD44hi/CD24lo/EpCAM+ breast CSCs, and importantly DUSP1 knockdown reduces CSC formation, while DUSP4 and DUSP6 knockdown enhance CSC formation, suggesting that DUSPs modulate EMT and CSC regulation in breast cancer differentially." (PMID 41158869, 2025). "Because proteasome inhibitors are a novel class of anti-tumor compounds, and there is evidence that DUSP1 regulates sensitivity to proteasome inhibitors in breast cancer through JNK activity, targeting DUSP1 enhances the anti-tumor efficacy of proteasome inhibitors." (PMID 41158869, 2025). "Furthermore, Krüpple-like transcription factor 5 (KLF5) promotes breast cancer cell survival partially through ERK-induced DUSP1 Ser359/364 phosphorylation, which is essential for DUSP1 protein stabilization." (PMID 31151270, 2019).
breast carcinoma (continued). "Moreover, our experimental results also demonstrated that shikonin induced the protein expression of both DUSP1 and DUSP2 in different types of breast cancer cells." (PMID 29422643, 2018). "Also, the results of qRT-PCR confirmed that shikonin induced the expression of both DUSP1 and DUSP2 in different types of breast cancer cells." (PMID 29422643, 2018). "Candas's study revealed a correlation between DUSP1 and HER2 expression in breast cancer." (PMID 27227569, 2016). "DUSP1 (also known as MKP-1), a member of the dual-specificity phosphatases (DUSPs) which interacted and catalyzed dephosphorylation of active MAPK, mediated anti-proliferative and anti-inflammatory actions of PR in the breast cancer." (PMID 26103053, 2015).
lung carcinoma (31 papers, 2010 to 2025). "High expression of DUSP1 is an independent risk factor that determines prognosis of early lung cancer patients." (PMID 29383165, 2017). "In addition, increased expression of DUSP1 has been implicated in lung cancer progression." (PMID 39495117, 2024). "DUSP1’s role in lung cancer is complex and context-dependent: Some studies suggest DUSP1 acts as a tumorigenic factor, while other studies suggest DUSP1 acts as a tumor suppressor." (PMID 41158869, 2025). "Studies found that high DUSP1 has been observed in various human cancers, including colon, bladder, gastric, breast, and lung cancer." (PMID 34336699, 2021). "The therapeutic effect of γ-secretase inhibition was also observed in lung cancer by the derepression of DUSP1 and inhibition of ERK." (PMID 31941156, 2020). "DUSP1 is reduced in various cancers, including liver cancer, pancreatic cancer, and lung cancer and this gene is considered a tumor suppressor that belongs to the MKP phosphatase family." (PMID 33056982, 2020). "That is, DUSP1 promotes prostate, colon, bladder, gastric, breast and lung cancer, but it exhibits anti-tumor effects in hepatocellular, as well as head and neck cancers." (PMID 31086176, 2019). "Further efforts are required to establish the role of DUSP1 in lung cancer." (PMID 41158869, 2025). "RNAi-mediated depletion of DUSP1 increases cisplatin sensitivity in NSCLC lung cancer cells." (PMID 41158869, 2025). "DUSP1 on the other hand plays a role in carcinogenesis, tumor progression and response to anti-cancer treatment, as expression of DUSP1 is essential for the resistance of lung cancer cell lines to cisplatin treatment." (PMID 37627150, 2023). "By targeting DUSP1/6, BCI induces apoptosis by ROS (reactive oxygen species) production and by activation of the intrinsic mitochondrial pathway in lung cancer H1299 cells." (PMID 41158869, 2025). "Forced lncRNA CASC9 expression promotes NSCLC cell proliferation and chemoresistance via epigenetic repression of DUSP1, and univariate and multivariate analyses reported that lncRNA CASC9 can be regarded as independent prognostic markers in lung cancer." (PMID 35685240, 2022). "Dual-specificity phosphatase 1 (DUSP1) has been found to inhibit migration and proliferation of gallbladder and lung cancer." (PMID 31579447, 2019). "Examining the 120 lung cancer samples, only UBE2C and dual specificity protein phosphatase 1 (DUSP1) had average CVs greater than 1 (1.06 and 1.04, respectively)." (PMID 29761043, 2018). "In lung cancer, the five most important mRNAs were HBB, HBA2, MT2A, ZFP36, and DUSP1." (PMID 39495117, 2024). "However, in lung cancer and head and neck SCC, the role of DUSP1 in tumor progression is still inconclusive." (PMID 27227569, 2016). "In further support of the negative role of DUSP1 in supporting lung cancer cell proliferation, treatment of mice with a γ-secretase inhibitor (LY-411575) reduced KRas(G12V)-driven NSCLC growth, while upregulating DUSP1 protein level and decreasing ERK1/2 phosphorylation." (PMID 40943262, 2025).